PAH (phenylalanine hydroxylase)
Diseases named in the same sentence as PAH in open-access papers (continued):
Sharing a sentence is not in itself a finding about the gene and the disease.
liver disease (2 papers, 2020 to 2025). "The observed elevation of phenylalanine and tyrosine in liver disease has been linked to oxidative stress-induced inhibition of phenylalanine hydroxylase." (PMID 40563298, 2025). "It should be noted that the activity of phenylalanine hydroxylase was reduced in biopsies from liver cirrhosis, alcoholic hepatitis and other liver diseases." (PMID 31963766, 2020). "Interestingly, it has been reported that only in the end-stage of liver disease the reaction catalyzed by phenylalanine hydroxylase may be impaired, and such defects can be corrected by transplantation." (PMID 31963766, 2020).
malaria (2 papers, 2014 to 2015). Malaria is a serious and sometimes fatal disease caused by a parasite that commonly infects a certain type of mosquito which feeds on humans. "The association of increased BH2 and low BH4/BH2 ratios with increased phenylalanine levels suggests that systemic deficiency of BH4 causes impaired phenylalanine hydroxylase function as well as NOS dysfunction in malaria." (PMID 25764397, 2015). "This could explain depression in both phenylalanine hydroxylase activity and NOS functionality in severe malaria." (PMID 25764397, 2015).
Obesity (2 papers, 2021 to 2025). Accumulation of substantial excess body fat. "Tyrosine, which is inversely associated with the risk of obesity, is synthesized from phenylalanine in a reaction catalyzed by phenylalanine hydroxylase, and affects the metabolism of glucose and lipids in the body." (PMID 34938762, 2021).
vitiligo (2 papers, 2020 to 2022). Generalized well circumscribed patches of leukoderma that are generally distributed over symmetric body locations and is due to autoimmune destruction of melanocytes. "On the other hand, low 4a-hydroxy-tetrahydrobiopterin dehydratase activity and the accumulation of 7-tetrahydrobiopterin were also detected in vitiligo patients, leading to the competitive inhibition of epidermal phenylalanine hydroxylase and influencing melanin synthesis." (PMID 33093609, 2020).
adenoma (1 paper, 2022). A neoplasm arising from the epithelium. "More recently, adenomas and an HCC were observed in an interim preclinical study to assess durability after AAV5-PAH in phenylalanine hydroxylase (PAH)-deficient mice, resulting in a clinical hold on the phase 1/2 study." (PMID 35690906, 2022).
COVID-19 (1 paper, 2022). A disease caused by infection with severe acute respiratory syndrome coronavirus 2. "In COVID-19, the considerable generation of ROS, due to cytokine activation, induces the irreversible non-enzymatic oxidation of 5, 6, 7, 8-tetrahydrobiopterin (BH4), a cofactor of phenylalanine 4-hydroxylase (PAH), the enzyme catalyzing the conversion of phenylalanine to tyrosine." (PMID 35391730, 2022).
endometrial cancer (1 paper, 2022). Primary or metastatic malignant neoplasm involving the endometrium (mucous membrane that lines the endometrial cavity). "It has been demonstrated that there is a significant relationship between high levels of phenylalanine due to a deficiency of phenylalanine hydroxylase and endometrial cancer, since it could affect the development or progression of endometrial cancer." (PMID 36291799, 2022).
endothelial dysfunction (1 paper, 2018). In vascular diseases, endothelial dysfunction is a systemic pathological state of the endothelium (the inner lining of blood vessels) and can be broadly defined as an imbalance between vasodilating and vasoconstricting substances produced by (or acting on) the endothelium. "However, small molecules that mimic the allosteric effects of L-phe at the GCH1-GFRP interface but do not bind to phenylalanine hydroxylase could be developed, underpinned by endothelial dysfunction." (PMID 29963647, 2018).
epilepsy (1 paper, 2025). A brain disorder characterized by episodes of abnormally increased neuronal discharge resulting in transient episodes of sensory or motor neurological dysfunction, or psychic dysfunction. "Group 2—Intermediate epilepsy/metabolic disorders (Ion-channel and neuronal-excitability phenotype): This group comprised patients harboring variants in SCN2A, PAH, IQSEC2, and GNPAT." (PMID 41300846, 2025).
heart failure (1 paper, 2024). Inability of the heart to pump blood at an adequate rate to meet tissue metabolic requirements. "Additionally, the process of C4-hydroxylation of phenylalanine into tyrosine, which serves as a precursor for catecholamines that are upregulated in senescence and heart failure, is catalyzed by phenylalanine hydroxylase." (PMID 38310264, 2024).
hyperlipidemia (1 paper, 2025). "Research has shown that phenylalanine hydroxylase converts L‐phenylalanine into L‐tyrosine, which has been identified as a potential biomarker for hyperlipidemia." (PMID 40735404, 2025).
ischemia (1 paper, 2025). A hypoperfusion of the BLOOD through an organ or tissue caused by a PATHOLOGIC CONSTRICTION or obstruction of its BLOOD VESSELS, or an absence of BLOOD CIRCULATION. "Similarly, observed alterations in phenylalanine and tyrosine metabolism likely indicate heightened oxidative stress and impaired phenylalanine hydroxylase (PAH) activity during acute ischemia." (PMID 40860967, 2025).
liver cancer (1 paper, 2020). An epithelial or non-epithelial malignant neoplasm that arises from the liver. "Therefore, our study provides a new insight about the expression pattern of Cdh1 and PAH in liver cancer tissues indicating its possible role in the progression of HCC." (PMID 33260674, 2020).
Parkinson disease (1 paper, 2019). A progressive degenerative disorder of the central nervous system characterized by loss of dopamine producing neurons in the substantia nigra and the presence of Lewy bodies in the substantia nigra and locus coeruleus. "Phenylalanine hydroxylase as a biomarker of Parkinson's disease also play important role in pathology development, even the detail mechanism is not well-known." (PMID 31998703, 2019).
prostate carcinoma (1 paper, 2022). A carcinoma that arises from epithelial cells of the prostate gland. "Downregulation of PAH and AOC1 and upregulation of DDC, LIN01436, and ORM1 were associated with the development of prostate cancer." (PMID 36497304, 2022).
SARS-CoV infection (1 paper, 2020). "Another study showed that phenylalanine hydroxylase (PAH) gene was downregulated in SARS-CoV infection leading to activation of immune system through upregulation of T helper 1 (Th1) responses." (PMID 32754004, 2020).
Wilms tumor (1 paper, 2021). An embryonal neoplasm characterized by the presence of epithelial, mesenchymal, and blastema components. "For Family 2 (Wilms tumor), the top-five ranked genes were FAM8A1, TRPM3, PAH, PCK1, and PCK2." (PMID 34624066, 2021).
metabolic disorder (64 papers, 2009 to 2026). "PKU (OMIM 261600) is a rare autosomal recessive metabolic disease caused by mutations in the gene encoding phenylalanine hydroxylase (PAH), an enzyme responsible for catalysing the hydroxylation of phenylalanine (Phe) to tyrosine (Tyr) in the liver." (PMID 40805990, 2025). "PKU is an autosomal recessive inherited metabolic disease caused by a deficiency in the phenylalanine hydroxylase (PAH) enzyme, which converts phenylalanine (phe) to tyrosine (tyr)." (PMID 38790566, 2024). "The original strain, SYNB1618, is an EcN-based LBT engineered to complement a disabling mutation in the host phenylalanine hydroxylase (PAH), which is the cause of the debilitating metabolic disease." (PMID 37929193, 2023). "Hyperphenylalaninaemia (HPA) is a rare, inherited metabolic disorder caused by variants in the gene encoding the enzyme phenylalanine hydroxylase (PAH), which catalyses the conversion of phenylalanine (Phe) to tyrosine (Tyr)." (PMID 34344399, 2021). "Phenylketonuria (PKU; OMIM 261600) is an inherited metabolic disorder caused by a mutation in the phenylalanine hydroxylase enzyme (PAH), which converts phenylalanine (Phe) into tyrosine." (PMID 31058098, 2019). "Mutations in mitochondrial DNA, most of which codes for the core ATP energy metabolism, mutations in genes coding for proteins responsible for transport of ATP from the mitochondrium to the cell, and mutations in the gene coding for phenylalanine hydroxylase all lead to severe metabolic disorders." (PMID 23825632, 2013). "Characterised by mutations in the hepatic enzyme phenylalanine hydroxylase (PAH), PKU is one of the most prevalent inborn metabolic disorders, with reported incidence rates around 1 in every 10,000 births." (PMID 31480383, 2019).
genetic disorder (15 papers, 2012 to 2024). "PKU (PKU; OMIM 261600) is an autosomal recessive genetic disease that results in a deficiency of phenylalanine hydroxylase (PAH; EC 1.14.16) to hydroxylate Phe to tyrosine (Tyr), using tetrahydrobiopterin as a cofactor." (PMID 30023287, 2018). "As many other inherited diseases the main pathologic mechanism in PKU is an enhanced tendency of the mutant phenylalanine hydroxylase (PAH) to misfold and undergo ubiquitin-dependent degradation." (PMID 23339306, 2012).
cancer (5 papers, 2011 to 2023). A tumor composed of atypical neoplastic, often pleomorphic cells that invade other tissues. "In our study, we highlight PAH as a novel candidate CPG that frequently harbors pathogenic variants in the pan-cancer dataset, and specifically in single-cancer types such as Lung-SCC." (PMID 38143269, 2023). "Phenylalanine is converted to tyrosine via catalytic oxidation by phenylalanine hydroxylase, and tyrosine is involved in the metabolism of glucose and fats in the body, which are the main energy sources for rapidly growing cancer cells." (PMID 37623893, 2023). "It has also been observed that phenylalanine hydroxylase activity may be sensitive to inflammation or cancer." (PMID 38067430, 2023).
tumor (5 papers, 2011 to 2025). "A four‐mRNA signature (CHRNA2, NPR3, VGLL3 and PAH) was found in primary tumour tissue samples from pN1 PCa patients, and then it was validated using the TCGA‐PRAD and GSE220095 datasets." (PMID 40219635, 2025). "The interference of the expression levels of SMS, P4HA1, PAH, PLOD2, and KYNU significantly decreased the invasion of tumor cells." (PMID 37511510, 2023). "The expression levels of SMS, ASNS, PLOD2, P4HA1, PAH, and KYNU were upregulated in tumor samples compared with normal samples, and the remaining three genes were downregulated." (PMID 37511510, 2023).
infection (3 papers, 2021 to 2023). The state of being infected such as from the introduction of a foreign agent such as serum, vaccine, antigenic substance or organism. "Indeed, Tg infection increases the level of dopamine but not that of serotonin and norepinephrine, indirectly via the release of inflammatory cytokines, but mostly directly via the presence in its genome of genes coding for phenylalanine hydroxylase and tyrosine hydroxylase." (PMID 34085752, 2021).
cardiovascular diseases (1 paper, 2019). "Phenylalanine hydroxylase (PAH) was associated with development of cardiovascular diseases, but this gene may be identified with advancement of CAD." (PMID 31881747, 2019).
PAH also shares sentences with these, for which no sentence is quoted: amino acid metabolism disorder (5 papers); congenital metabolic disorder (3); Hypertension (3); methylmalonic acidemia (3); carnitine deficiency (2); homocystinuria (2); maple syrup urine disease (2); microcephaly (2); Osteopenia (2); Acidosis (1); acyl-CoA dehydrogenase deficiency (1); alcoholic hepatitis (1); Alpha-thalassemia (1); Alport syndrome (1); atherosclerosis (1); autism (1); autosomal recessive deafness (1); Charcot-Marie-Tooth disease (1); cobalamin deficiency (1); congenital adrenal hyperplasia (1); convulsion (1); developmental disabilities (1); diabetes (1); hepatic insufficiency (1); kidney disease (1); liver cirrhosis (1); malnutrition (1); melanoma (1); metabolism (1); Methylmalonic aciduria (1).
A further 9 diseases each share a sentence with PAH in 1 paper.